SNHG8 (small nucleolar RNA host gene 8)
Synonyms: NCRNA00060; LINC00060
Gene: Long non-coding RNA gene on chromosome 4 (118,278,462 to 118,285,316, forward strand). Ensembl gene ENSG00000269893.
Gene Ontology:
Biological process: RNA processing
Cellular component: nucleolus
Diseases named in the same sentence as SNHG8 in open-access papers:
SNHG8 is named in the same sentence as 36 diseases in open-access papers, as found by Europe PMC text mining. Sharing a sentence is not in itself a finding about the gene and the disease. The quoted sentences say what the papers report.
gastric cancer (17 papers, 2016 to 2025). A primary or metastatic malignant neoplasm involving the stomach. "In survival analysis, elevated fasting blood glucose (P =0.007) and high SNHG8 expression (P =0.007) were significantly associated with shorter survival times in gastric cancer." (PMID 30299268, 2018). "When fasting blood glucose and SNHG8 expression were up-regulated simultaneously, the risk of gastric cancer mortality increased significantly (P = 0.001)." (PMID 30299268, 2018). "The result revealed high SNHG8 expression was significantly associated with poor prognosis in gastric carcinoma patients." (PMID 30299268, 2018). "In our study, we had proved that high SNHG8 expression with shorter survival time was associated with poor clinical outcome of gastric carcinoma patients." (PMID 30299268, 2018). "Interestingly, SNHG8 is overexpressed in various tumors and it is associated with cancer cell growth and metastasis of tumors, such as colorectal cancer and gastric carcinoma." (PMID 40202183, 2025). "Previous research has also demonstrated that EBV infection can modulate the expression of various lncRNAs, such as SNHG8 in gastric cancer and MALAT1, AFAP1-AS1, and AL359062 in nasopharyngeal carcinoma." (PMID 39684278, 2024). "SNHG8 has been largely studied in the context of tumorigenesis, where it has been shown to promote the proliferation and invasion of cancer cells in gastric cancer, breast cancer, and ovarian cancer." (PMID 37730840, 2023). "Although numerous observations have demonstrated HOXA-AS2 and SNHG8 play vital roles in the development of various cancer including non-small cell lung cancer and breast cancer, gastric cancer." (PMID 33520460, 2021). "SNHG8 has been confirmed to act as a ceRNA in cancers including esophageal squamous cell carcinoma and gastric cancer." (PMID 34874227, 2021). "Small nucleolar RNA host gene 8 (Snhg8) is upregulated in human gastric cancer cells, and knockdown of Snhg8 inhibits cell growth." (PMID 31165722, 2019). "Based on our analysis of SNHG8 and EBV targets, we propose a theory of how SNHG8 triggers gastric cancer." (PMID 27835598, 2016). "Our results reveal the intertwined tumorigenesis mechanisms of lncRNA and EBV and identify SNHG8 as a highly possible candidate biomarker and drug target of gastric cancer." (PMID 27835598, 2016). "Similarly, SNHG8 was considered to be an oncogenic factor and was upregulated in various types of cancer, such as gastric cancer, melanoma, nasopharyngeal cancer, and esophageal cancer." (PMID 35910212, 2022). "Sixty-one cases of EBVaGC, 20 cases of non-EBV-infected gastric cancer (EBVnGC), and relative cell lines were studied for the expression of SNHG8 and BHRF1 (BCL2 homolog reading frame 1) encoded by EBV with Western blot and qRT-PCR assays." (PMID 34722282, 2021). "In gastric cancer, SNHG8 enhances cell proliferation and invasion." (PMID 34362407, 2021). "SNHG8, located on 4q26, regulates tumorigenesis and metastasis and controls the progression of multifarious diseases, such as hepatocellular carcinoma, pancreatic adenocarcinoma, endometrial carcinoma, and gastric carcinoma." (PMID 34456632, 2021). "In conclusion, our findings convincingly demonstrated that elevated fasting blood glucose and high SNHG8 expression could predict poor prognosis after radical gastrectomy for gastric cancer patients." (PMID 30299268, 2018). "SNHG8 acting as a proto-oncogene promoted gastric carcinoma development." (PMID 30299268, 2018). "Further, the expression of small nucleolar RNA host gene 8 (SNHG8), a long non-coding RNA, is markedly increased in EBVaGC compared with that in EBV-negative gastric cancers or normal gastric mucosa." (PMID 36672418, 2023). "SNHG8, a family member of small nucleolar RNA host genes (SNHG), has been reported to act as an oncogene in gastric carcinoma (GC)." (PMID 34722282, 2021). "In gastric cancer, elevated FBG and high SNHG8 expression resulted in poor survival outcomes after radical gastrectomy." (PMID 33287763, 2020).
gastric cancer (continued). "The expression of small nucleolar RNA host gene 8 (SNHG8) in cultured EBV positive GC cells is significantly higher than that in noncancerous gastric mucosa cells or EBV-negative gastric cancer tissues." (PMID 32272952, 2020).
non-small cell lung carcinoma (6 papers, 2020 to 2025). A group of at least three distinct histological types of lung cancer, including non-small cell squamous cell carcinoma, adenocarcinoma, and large cell carcinoma. "Additionally, SNHG8 has been identified as a potential biomarker and therapeutic target for hepatocellular carcinoma and non-small cell lung cancer." (PMID 39530098, 2024). "For example, Chen found that SNHG8 was upregulated in non-small cell lung cancer." (PMID 35686101, 2022). "For example, Chen found that SNHG8 overexpressed in non-small cell lung carcinoma (NSCLC), and Dong found that SNHG8 is an oncogene in human hepatocellular carcinoma, Meng found SNHG6 promotes glioma tumorigenesis in glioma, and Zhu found SNHG4 overexpressed in hepatocellular carcinoma." (PMID 31967298, 2020).
hepatocellular carcinoma (5 papers, 2017 to 2024). A malignant tumor that arises from hepatocytes. "Moreover, SNHG8 acts as a sponge of miR-149 to regulate the tumorigenesis and metastasis of hepatocellular carcinoma." (PMID 34362407, 2021). ",SNHG8 promotes hepatocellular cancer tumorigenesis by sponging miR-149-5p." (PMID 34362407, 2021).
breast carcinoma (4 papers, 2021 to 2023). "For instance, in breast cancer, SNHG8 accelerates cell migration and proliferation by miR-335-5p and PYGO2." (PMID 35067159, 2022). "Previous studies reported that SNHG8 often plays an oncogenic role in numerous cancers, such as breast cancer, colorectal cancer, and cancer." (PMID 35067159, 2022). "For instances, SNHG8 promotes the breast cancer cells proliferation by regulating the miR-335-5p/PYGO2 axis and accelerates ovarian cancer progression by miR-1270/ S100A11 axis." (PMID 35067159, 2022). "al. also verified that SNHG8 modulates miR-634/ZBTB20 axis to promote breast cancer progression." (PMID 35067159, 2022).
colorectal cancer (4 papers, 2021 to 2025). A primary or metastatic malignant neoplasm that affects the colon or rectum. "Knockdown of SNHG8 via sponging of SNHG8 with miR-663 significantly promoted the migration, proliferation and invasion of colorectal cancer." (PMID 35438133, 2022). "Additionally, SNHG8, up-regulated in colorectal cancer tissues and cells, was testified to exert its tumor promoting impacts on colorectal cancer through sponging miR-663." (PMID 35101035, 2022). "For instance, SNHG8 accelerates cell growth through sponging miR-663 in colorectal cancer cells." (PMID 34362407, 2021). "In colorectal cancer, SNHG8 accelerates the growth, migration and invasion of cells." (PMID 34362407, 2021).
esophageal squamous cell carcinoma (4 papers, 2020 to 2021). Esophageal squamous cell carcinoma (ESCC) is a type of esophageal carcinoma (EC) that can affect any part of the esophagus, but is usually located in the upper or middle third. "In addition, SNHG8 is highly expressed in esophageal squamous cell carcinoma and high SNHG8 expression is closely associated with TNM stage and worse overall survival among patients with esophageal squamous cell carcinoma." (PMID 34362407, 2021). "SNHG8 plays oncogenic roles in the malignancy of esophageal squamous cell carcinoma by sponging miR-411, thus increasing KPNA2 expression." (PMID 32248842, 2020). "Moreover, SNHG8 has been found to be upregulated in esophageal squamous cell carcinoma and to directly sponge miR-411 to increase oncogenicity." (PMID 33816305, 2021).
nasopharyngeal carcinoma (4 papers, 2022 to 2025). A carcinoma arising from the nasopharyngeal epithelium. "For example, upregulation of APAF1-AS1, AL359062, and MALAT1 in nasopharyngeal carcinoma (NPC) and SNHG8, RP5-1039 K5.19, and TP73-AS1 in EBV associated-gastric cancer can be associated with cancer promotion." (PMID 39941858, 2025). "In addition, a large number of studies indicated that SNHG8 serves as a cancer-promoter in ovarian cancer, prostate cancer, and nasopharyngeal carcinoma." (PMID 35067159, 2022).
ovarian carcinoma (4 papers, 2020 to 2025). A malignant neoplasm originating from the surface ovarian epithelium. "By searching related literature and databases, about 30% lncRNAs have been verified to play roles in the regulation of proliferation, invasion, and migration of ovarian cancer cells, including ZFAS1, SNHG1, GAS5, EMX20S, GIHCG, TP53TG1, EPB41L4A-AS1, SNHG8, SNHG6, and HCP5." (PMID 33519912, 2020).
Cerebral ischemia (3 papers, 2022 to 2023). Restriction of arterial blood supply to the brain associated with insufficient oxygenation to support the metabolic requirements of the tissue. "Our results are also in accordance with previous study demonstrating the protective role of the Snhg8/miR-384/Hoxa13/FAM3A axis in cerebral ischemia-induced neuronal apoptosis." (PMID 34853925, 2023). "The Snhg8/miR-425-5p/SIRT1/NF-κB axis plays a critical role in regulating cerebral ischemia-induced microglial inflammation and brain-blood barrier damage." (PMID 36275741, 2022). "Therefore, SNHG8, as an endogenous competitive RNA, adsorbs miR-425-5p to regulate SIRTI/NF-KB to reduce the inflammatory response of cerebral microvascular endothelial cells and microglia induced by cerebral ischemia/reperfusion, and protect the blood brain barrier of MCAO/R mice." (PMID 36275741, 2022).
myocardial infarction (3 papers, 2022 to 2025). Gross necrosis of the myocardium, as a result of interruption of the blood supply to the area, as in coronary thrombosis. "However, the complex of periostin, miR-203-3p, and small nucleolar RNA host gene 8 (Snhg8) mediated neonatal mouse cardiomyocytes (NMCMs) apoptosis after hypoxia-treated NMCMs, contributing to acute myocardial infarction." (PMID 36611844, 2022). "However, SNHG8 also affects myocardial infarction by promoting activity in the NF‐κB pathway." (PMID 35659362, 2022).
endometrial carcinoma (2 papers, 2021). A malignant tumor arising from the epithelium that lines the cavity of the uterine body. "In endometrial carcinoma, the knockdown of SNHG8 represses cell viability." (PMID 34362407, 2021).
esophageal cancer (2 papers, 2022). A primary or metastatic malignant neoplasm involving the esophagus. "Knockdown of SNHG8 suppresses the progression of esophageal cancer by modulating the miR-1270/BACH1 axis." (PMID 35067159, 2022). "Here in this study, the role of lncRNA SNHG8 in esophageal cancer was uncovered by a series of functional experiments." (PMID 35067159, 2022). "The subsequent results indicated that knockdown of SNHG8 suppresses the progression of esophageal cancer." (PMID 35067159, 2022). "In this study, we verified that lncRNA SNHG8 participates in regulating the progression of esophageal cancer." (PMID 35067159, 2022). "This study dedicates to clarify the role of lncRNA SNHG8 in esophageal cancer and how SNHG8 functions in esophageal cancer." (PMID 35067159, 2022). "As the result shown, the expression of SNHG8 in esophageal cancer tissues are significantly enhanced than whose in normal tissues (P = 0.00034)." (PMID 35067159, 2022). "To investigate how SNHG8 exerts its function in esophageal cancer, we first analyzed the downward target of SNHG8." (PMID 35067159, 2022). "To summarize, our findings are agreed with the numerous reports that SNHG8 should be an oncogene participating in regulating the progression of esophageal cancer." (PMID 35067159, 2022). "To clarify the role of SNHG8 in esophageal cancer, we constructed a lentivirus shRNA to reduce the expression of SNHG8." (PMID 35067159, 2022). "The subsequent results verified that knockdown of SNHG8 suppresses the progression of esophageal cancer by modulating the miR-1270/BACH1 axis." (PMID 35067159, 2022). "In our study, we revealed that lncRNA SNHG8 should be an oncogene participating in regulating the progression of esophageal cancer." (PMID 35067159, 2022). "Yet, few studies discussed how SNHG8 performs in esophageal cancer." (PMID 35067159, 2022). "Meanwhile, the expressions of SNHG8 in esophageal cancer cell lines were examined." (PMID 35067159, 2022). "Thus, we concluded that knockdown SNHG8 suppresses the progression of esophageal cancer by modulating the miR-1270/BACH1 axis." (PMID 35067159, 2022). "Although we have identified the anticancer role of SNHG8 in esophageal cancer, there could still be other mechanisms of how SNHG8 regulates cancer progression." (PMID 35067159, 2022). "All in all, our data suggested that knockdown SNHG8 inhibits the progression of esophageal cancer." (PMID 35067159, 2022). "To test this conjecture, we knocked the expression level of SNHG8 down in esophageal cancer cells to obverse whether the malignant behaviors are influenced." (PMID 35067159, 2022). "Therefore, the role and functional mechanism of SNHG8 in esophageal cancer need to be further clarified." (PMID 35067159, 2022). "Knockdown SNHG8 could suppress the progression of esophageal cancer, which implies SNHG8 could be used as a therapeutic target in esophageal cancer." (PMID 35067159, 2022).
glioma (2 papers, 2020 to 2022). A benign or malignant brain and spinal cord tumor that arises from glial cells (astrocytes, oligodendrocytes, ependymal cells). "Other investigators found that the expression trend of SNHG8 in glioma and liver cancer was consistent with these studies." (PMID 35686101, 2022).
pancreatic adenocarcinoma (2 papers, 2021). "SNHG8 is up-regulated in pancreatic adenocarcinoma and the pancreatic adenocarcinoma patients with higher expression of SHNG8 are accompanied with shorter overall survival." (PMID 34362407, 2021).
Alzheimer disease (1 paper, 2023). A progressive, neurodegenerative disease characterized by loss of function and death of nerve cells in several areas of the brain leading to loss of cognitive function such as memory and language. "SNHG8 was significantly reduced in FTLD-tau caused by MAPT IVS10 + 16 or p.P301L; a primary sporadic tauopathy, progressive supranuclear palsy; and a secondary tauopathy, Alzheimer’s disease." (PMID 37730840, 2023).
Huntington disease (1 paper, 2016). Huntington disease (HD) is a rare neurodegenerative disorder of the central nervous system characterized by unwanted choreatic movements, behavioral and psychiatric disturbances and dementia. "Interestingly, genes in two neurodegenerative diseases, Huntington’s disease (HD) and Parkinson’s disease (PD) are potentially regulated by lncRNAs, such as PPP3CB-AS1, SNHG8 and DARS-AS1." (PMID 27496175, 2016).
osteosarcoma (1 paper, 2021). A usually aggressive malignant bone-forming mesenchymal neoplasm, predominantly affecting adolescents and young adults. "According to recent studies, SNHG8 contributes to the cell proliferation of osteosarcoma via binding to miR-542-3p." (PMID 34362407, 2021).
Sepsis (1 paper, 2025). Sepsis is defined as life-threatening organ dysfunction caused by a dysregulated host response to infection. "The cell percentage graph indicated that PADI4+ neutrophils, CD177+ neutrophils, and SNHG8+ neutrophils were significantly increased in sepsis tissues." (PMID 40666706, 2025).
tauopathy (1 paper, 2023). Neurodegenerative disorders involving deposition of abnormal tau protein isoforms (tau proteins) in neurons and glial cells in the brain. "Genetic manipulation of SNHG8 leads to reduced stress granule formation suggesting that dysregulation of this non-coding RNA is a causal factor driving stress granule formation in tauopathies." (PMID 37730840, 2023). "Among these lncRNAs, SNHG8 was significantly reduced in a mouse model of tauopathy and in the brains of patients with tauopathy, supporting a role for SNHG8 in pathologic processes." (PMID 37730840, 2023). "Together, we show SNHG8 is altered in iPSC and mouse models of tauopathy and in tauopathy patient brains, supporting a role for SNHG8 in pathologic processes." (PMID 37730840, 2023). "Rescuing SNHG8 expression leads to reduced stress granule formation and reduced TIA1 levels in immortalized cells and in MAPT mutant neurons, suggesting that dysregulation of this non-coding RNA is a causal factor driving stress granule formation via TIA1 in tauopathies." (PMID 37730840, 2023). "Thus, we sought to determine whether SNHG8 is altered in human brains of tauopathy patients." (PMID 37730840, 2023). "Interestingly, our findings that stress alone was sufficient to reduce SNHG8 and promote stress granule formation provides a possible explanation for a sporadic tauopathy, PSP, where SNHG8 is significantly reduced in PSP patient brains." (PMID 37730840, 2023).
vascular tumor (1 paper, 2021). "The overexpression of SNHG8 had a significant correlation with tumor size (p = 0.036) and vascular tumor thrombus (p = 0.024)." (PMID 34722282, 2021).
viral infection (1 paper, 2025). "Activation of tissue repair mechanism (SNHG8) was also observed, further underscoring evidence of physiologically relevant AT2 response to viral infection." (PMID 40920821, 2025).
Wilms tumor (1 paper, 2021). An embryonal neoplasm characterized by the presence of epithelial, mesenchymal, and blastema components. "Thus, it is biologically possible that changes of the expression and splicing of SNHG8 and RP11-384 K6.6 caused by SNP rs1064034 and rs298982 may influence Wilms tumor risk." (PMID 34863142, 2021).